CCL20 (C-C motif chemokine ligand 20)
Diseases named in the same sentence as CCL20 in open-access papers (continued):
Sharing a sentence is not in itself a finding about the gene and the disease.
cancer (continued). "The chemokin gene, CCL20, which recruits regulatory T cells and largely contributes to the progression of a variety of cancers, was expressed in the subtype M_C3_CCL20." (PMID 35102420, 2022). "Remarkably, an increasing number of studies have recently drawn attention to the association of CCL20 and its receptor CCR6 in the oncogenesis of various types of cancers." (PMID 34733778, 2021). "The available evidence supports the role of CCL20 in the progression of inflammatory diseases, including cancers." (PMID 34569432, 2021). "Here, we report that under acute ER stress C/EBPδ is induced by the PERK pathway to contribute to the induction of the chemokines CXCL8 and CCL20, thus revealing a novel mechanism for ER stress-mediated modulation of cancer cells’ microenvironment." (PMID 34725321, 2021). "In contrast, the identified chemokine CCL20 represents a factor that can affect cancer cells in an autocrine and paracrine manner promoting cancer progression by enhancing cancer cell migration and proliferation." (PMID 34671021, 2021). "These advances have led to the recognition of CCL20 as a promising candidate for cancer immunotherapy." (PMID 34569432, 2021). "Past studies showed that CCL20 was used by cancer cells for physiological functions involving tumorigenesis, angiogenesis, invasion, and metastasis." (PMID 33802643, 2021). "Recently, the expression and clinical relevancy of CCL20 in human cancers has been documented by a number of studies 28-30." (PMID 33123272, 2020). "CCL20 has been recently correlated with malignant phenotypes (uncontrolled cell proliferation, invasion, metastasis, etc.)in many cancers." (PMID 33123272, 2020). "In the cancer microenvironment, cancer cells secrete chemokine (e.g., CCL20) to recruit Treg and also express the immune checkpoint molecule to suppress the immune response." (PMID 32664248, 2020). "The chemokine ligand 20 (CCL20) is able to recruit T helper cells to maintain the immunosuppressive microenvironment and ensure the progression of the cancer." (PMID 32503307, 2020). "ROC analysis showed that serum CCL20 level had a sensitivity of 78.9% and a specificity of 77.2% with reference to cancer recurrence (cutoff value: 64.0 pg/ml, AUC=0.882)." (PMID 33123272, 2020). "The chemokine receptor 6 (CCR6) is a secondary target of CCL20 that induces cancer migration and metastasis." (PMID 32503307, 2020). "Most of the genes in the subnetworks were inflammatory cytokines and participated in TNF signaling pathways and pathways in cancer, such as Ccl2, Ccl20, Csf1, Cx3cl1, Cxcl1, Cxcl3, Il6, Birc3, Map3k8, Nos2, Nfkb2, Tnfrsf1b, and Vcam1." (PMID 33042984, 2020). "CCL20 expression is elevated in many cancers, such as breast cancer, hepatocellular carcinoma, and pancreatic cancer." (PMID 33076281, 2020). "The cancer cells enable stromal ones to up-regulate CCL20 thanks to the paracrine trigger of the molecular cascade by the activation of the transcription factor CCAAT enhancer binding protein beta (C/EBPβ) and to the release of IL6." (PMID 31096567, 2019). "CCL20 belongs to CC chemokine family and plays key roles in the development of different kinds of cancers." (PMID 30760665, 2019). "The expression of CXCL1, CXCL3, CXCL2, CCL20, and IL6 are enriched in residual cancer and are associated with lesser response the chemotherapy when highly expressed at baseline." (PMID 30967156, 2019). "CCL20 and IL-17A were identified as candidate biomarkers using multiplex assay and pan-cancer screening of TCGA data." (PMID 31387598, 2019). "In our study, we also found a close correlation between the chemokine CCL20 and drug resistance in cancer." (PMID 31395078, 2019). "The CCR6/CCL20 axis thus demonstrates a vital role in determining the disease outcome of inflammatory disorders and cancer metastasis in multiple organ systems in the human body." (PMID 30004409, 2018).
cancer (continued). "Inventors of this novel compound discovered the overexpression of CCL20 in CSCs and targeted their invention to inhibit CCL20 activity in cancers exhibiting cells with a CSC phenotype." (PMID 30453514, 2018). "CCL20 has been reportedly expressed in varied human cancer types, such as melanoma, adenocarcinoma, hepatocellular carcinoma leukemia, lymphoma, prostate cancer, colorectal, oral and lung squamous cell carcinoma and pancreatic carcinoma (PCA)." (PMID 30004409, 2018). "Our results showed that, in comparison to vector cells, the intracellular drug abundance in CCL20-overexpressing cancer cells was decreased by 50%, and more docetaxel was accumulated in the extracellular supernatant." (PMID 30052635, 2018). "Several pro-inflammatory cytokines and their associated pathways, which are known to promote cancer cell proliferation in many cases, were implicated in typical responders throughout this study, including IL6, CCL20, CXCL8, TNF signaling, and IL-17 signaling." (PMID 29983870, 2018). "More recently, a paper demonstrated that the HIF-1a/CCL20/IDO axis plays a crucial role in accelerating cancer metastasis in hepatocellular carcinoma by inducing EMT and an immunosuppressive tumor microenvironment." (PMID 29197379, 2017). "Among these, CCL20 has been proven to be related to invasion and metastasis in some types of cancer." (PMID 29212174, 2017). "Simultaneously, HIF‐1α binds to a HRE (hypoxia response element) on the CCL20 promoter and induces CCL20 expression by cancer cells." (PMID 28599100, 2017). "In conclusion, we summarized that RANK/RANKL up-regulated the expression and secretion of CCL20 in EC cells, which accelerated migration/invasion and promoted cancer progression through EMT." (PMID 27015366, 2016). "Collectively, these findings indicate that circulating CCR6 and CXCR6-expressing MAIT cells can be easily attracted into the cancer tissues releasing the corresponding chemokines, such as CCL20 and CXCL16, respectively, in MAC patients." (PMID 27517754, 2016). "CCL-20 is expressed by different tumors, where it contributes to cancer cell growth and in vivo invasion." (PMID 27322553, 2016). "The chemokine CCL20 has been reported to promote cancer cell proliferation and migration through the chemokine receptor CCR6." (PMID 26248031, 2015). "Proinflammatory molecules such as IL-17, CCL20, S100A8, S100A9, and S100A8/A9 have been shown to be implicated in many types of cancer." (PMID 26273651, 2015). "Chemokine receptor 6 (CCR6) and its ligand, CCL20, were highly expressed in a variety of human cancers." (PMID 24743888, 2014). "Colony assays, ERK signaling and chemokine production were measured to assess cancer cell responsiveness to CCL20 and IL-17 stimulation." (PMID 21949768, 2011). "We demonstrated that in the co-culture both macrophages and CMT93 cancer cells produced increased levels of CCL20 compared with either macrophages or CMT93 culture alone." (PMID 21559338, 2011). "Both CMT93 cancer cells and macrophages produced a large amount of CCL20, the sole ligand of CCR6 in vitro and in vivo." (PMID 21559338, 2011). "In PCA tissues CCL20 immunoreactivity was detected in the cytoplasms of ductal epithelial cancer cells." (PMID 20459729, 2010). "Expression of CCL20 has been confirmed in various human cancer entities, such as leukaemia, lymphoma, melanoma, hepatocellular carcinoma, prostate cancer, colorectal adenocarcinoma and lung and oral squamous cell carcinoma." (PMID 20459729, 2010). "In order to further determine the involvement of CCL20 in cancer development in vitro, we introduced the CCL20 gene into prostate PC3 cells which express the CCR6 receptor." (PMID 19340288, 2009). "Having established the role of CCL20 in cancer development in vivo, we evaluated the effect of neutralizing antibodies to human CCL20 on the growth of CCL20-and CXCR4 overexpressing PC3 cells." (PMID 19340288, 2009).
cancer (continued). "In this study, we precisely define what cells produce CCL20 in pancreatic inflammation and cancer." (PMID 42039489, 2026). "Notably, chemokines such as CXCR4 and CCL20, both located within the pink module, are known to promote carcinogenesis, angiogenesis, and the survival of cancer cells." (PMID 41357186, 2025). "This increasing knowledge will open the door to developing effective anticancer combination therapies that can reverse CCL20-mediated chemotaxis of immunosuppressive cells including neutrophils, macrophages, Tregs, and MDSCs while enhancing immune-mediated destruction of cancer." (PMID 39985603, 2025). "CCL20 is a chemokine with notable signaling functions in the context of cancer." (PMID 40114916, 2025). "Also, an outline of studies utilizing CCL20 in combination with other standard cancer treatments has been shed." (PMID 39985603, 2025). "Given the altered expression of CCL20 in the Cat D KO cancer cells, we sought to determine whether CCL20 functioned as a coregulator of Cat D-mediated TAM polarization." (PMID 38297161, 2024). "CCR6 binds with its ligand CCL20, promoting cancer progression." (PMID 39273632, 2024). "Mechanismly, PD-L2 bound its receptor Repulsive guidance molecule B (RGMB) on cancer cells and activated extracellular signal-regulated kinase (Erk) and nuclear factor κB (NFκB), leading to increased production of chemokine CCL20, which recruited Tregs and contributed to NSCLC progression." (PMID 39042313, 2024). "Notably, activation of the NF‐κB signalling pathway is responsible for the regulation of CCL20‐mediated proliferation, invasion and metastasis of many types of cancer cells." (PMID 38809918, 2024). "At the single‐cell level in non‐responders, nearly all immuno‐suppressive/exhausted markers as PD‐1, CTLA4, and BTLA, along with CCR6, a receptor comprising CCR6/CCL20 axis and promoting cancer progression, elevated consistently in peripheral HLA‐DR+CD8+ T cells." (PMID 39467150, 2024). "Additionally, CCL20 encourages tumour microenvironment remodelling processes, which are essential to metastatic processes in many cancers." (PMID 39674881, 2024). "Notably, CCL20, a chemokine that induces macrophage polarization into the M2 subtype, was significantly reduced in the Cat D KO cancer cells at both the protein and mRNA levels." (PMID 38297161, 2024). "Infiltrating immune cells showed active CXCL16 and CCL20 signalling, which aid cancer progression." (PMID 39149248, 2024). "A major role of CCL20 in cancer is its involvement in cancer metastasis." (PMID 36447119, 2023). "Moreover, the upregulated expression of SOD2, IL1B, PLAUR, CXCL3, and CCL20 promoting cancer cell invasion in other tumors depended on the NF-κB mechanism." (PMID 37954130, 2023). "Besides, six factors had inverse causal associations with cancer, including CCL15, CCL18, CCL19, CCL20, CCL21, and CCL28." (PMID 38075694, 2023). "Moreover, CCL20 can promote cancer progression through direct effects on cancer cells and indirectly by remodeling the tumor microenvironment." (PMID 37016172, 2023). "In addition, the generality of the oncogenic impact of CCL20 in other cancer types warrants further validation." (PMID 35864953, 2022). "In addition, CXCL1 expression was extremely correlated with CCL20, CXCL8 and CXCL3 cancer-associated chemokines expression." (PMID 35764974, 2022). "Furthermore, CCL20 was also included in the survival-predicting genes and was mainly expressed in cancer cells of branch II." (PMID 35480896, 2022). "The role of CCL20 in cancer is dependent on the specific cancer context." (PMID 35864953, 2022). "Importantly, we further found that CCL20 was up-regulated in PCa tissues compared with para-cancer tissues via IHC assay." (PMID 36045408, 2022). "CCL20/CCR6 axis works on cancer cells in autocrine and paracrine manners." (PMID 35864953, 2022). "TAM favors CCL20 production by cancer cells through their secretion of TNF-α, IL-1β and IL-6." (PMID 33924428, 2021).
cancer (continued). "CCL20 plays crucial roles in promoting cell proliferation and migration in human cancers." (PMID 33681225, 2021). "have reported that CCL20 stimulation promoted cancer cell proliferation and migration in vitro." (PMID 34733778, 2021). "Therefore, an in-depth understanding of the roles and regulatory mechanisms of CCL20 are relevant for the development of cancer drugs with improved efficacies." (PMID 34569432, 2021). "We speculate that close collaboration of cancer cells and macrophages induce some sort of unknown inflammatory alteration, which may be a trigger for the induction of CCL20 in the oral carcinogenic process." (PMID 34178651, 2021). "HGF is known to be involved in migration of many cancer cell types, and a few reports have indicated that it may induce CCL20 secretion." (PMID 34853656, 2021). "The chemokines CXCL8 and CCL20 are modulators of immune cells as well as cancer cells." (PMID 34725321, 2021). "In addition, the composition of the gut microbiota, by triggering Toll-like receptor (TLR) signaling in cancer cells, can promote their CCL20 production." (PMID 33924428, 2021). "Based on these findings, CCL20 has become a potential therapeutic target for cancer immunotherapy." (PMID 34569432, 2021). "In addition, the Th17 subpopulation stimulates cancer cells to secrete CCL20, a chemokine that enhances migration of dendritic cells to the TME." (PMID 32148497, 2020). "Importantly, although TFF1 is predominantly expressed by cancer cells, the authors detected CCL20, CXCL1, and IL-8 in cancer cells and also in the surrounding stroma." (PMID 32373132, 2020). "Disruption of CCL20/CCR6 signaling would therefore be an alternative approach for cancer treatment." (PMID 32194362, 2020). "Several reports have indicated that CCL20 has a direct impact on cancer cells." (PMID 31561620, 2019). "To further evaluate the effect of 5-FU on CCL20 expression in cancer cells, we determined the mRNA expression of CCL20 in SW620 and DLD-1 cells after treatment with 5-FU, and found that CCL20 was significantly increased especially at 48 h, in a dose-dependent manner." (PMID 31395078, 2019). "A. The expression of CCL20 and IL-17A from TCGA database in 18 kinds of cancer tissues." (PMID 31387598, 2019). "Finally, we observed that CCL20 and IL-17A levels were both positively associated with levels of CD44 and MMP3, which are closely related to cancer progression." (PMID 31387598, 2019). "The result showed that CCL20 was indeed derived from CD326+ cancer cells." (PMID 31395078, 2019). "In conclusion, CCL20 significantly promoted the progression of TNBC both in vitro and in vivo, and it was preliminarily shown that CCL20 could promote the resistance of cancer cells to taxane." (PMID 30052635, 2018). "Similarly, in pancreatic cancer, CCL20 released from TAMs enhances the invasiveness of cancer cells via its unique receptor CCR6." (PMID 29197379, 2017). "Notably, several of the cytokines whose expression was upregulated in parenchymal cancer cells (e.g. CCL2, CCL7, CXCL1, CXCL2, CXCL5, CCL20) have been implicated in the attraction of immune cells." (PMID 27203741, 2016). "Among them, CCL20 had proved to be related to invasion and metastasis in some types of cancer." (PMID 27015366, 2016). "In summary, all data supported the hypothesis that RANK/RANKL elevated the expression and secretion of CCL20 in EC cells, which promoted cancer progression through EMT." (PMID 27015366, 2016). "The high expression of CCL20 may contribute to the selective recruitment of CCR6 positive cancer cells and metastases formation." (PMID 26626416, 2015). "The liver may then selectively attract cells to attach and form micrometastases, perhaps by binding to putative integrin-like adhesion molecules that are possibly either induced or activated on cancer cells via CCL20/CCR6 interaction." (PMID 24979261, 2014). "We therefore next tested by ELISA the expression of CCL20 in a range of human cancer cell lines." (PMID 19340288, 2009).
cancer (continued). "Co-expression of CXCR4 and CCL20 in the same cancer cells was observed." (PMID 19340288, 2009). "Altogether, our findings for the first time provide evidence for existence of a putative CXCR4/CCL20 interaction that could be involved in cancer development processes." (PMID 19340288, 2009). "Altogether, our findings provide evidence for the existence of a putative CXCR4/CCL20 interaction that could be involved in cancer development processes." (PMID 19340288, 2009). "Further studies are necessary to determine whether CCL-20 behaves in a similar fashion in human cancer cells." (PMID 16375766, 2005). "However, the correlation between CCL20 and programmed cell death in cancer is unclear, so we further investigated whether CCL20 expression affects cell death and cell proliferation." (PMID 35864953, 2022). "EPS-R1 could be used as an adjuvant therapy in patients with CCL20-producing cancers." (PMID 36726985, 2022). "However, the mechanism of the CCL20/LARC expression increase depends on the type of cancer." (PMID 32781743, 2020). "It has been reported that the expression levels of CCL20 and CCR6 are increased in many cancers such as gliomas, and colorectal and pancreatic cancers, and the increased expression of these molecules is closely associated with poor prognosis in cancer patients." (PMID 26789110, 2016). "The CCL20/CCR6 axis contributes to the activation of NF-kB and secretion of MMP-3, which promote cancer cell invasion and migration." (PMID 40150133, 2025). "A study integrating three datasets revealed enhanced expression of CCL20 in SPP1+ macrophages, which is believed to facilitate cancer cell migration and proliferation, while remodeling the TME to accelerate cancer progression." (PMID 40191203, 2025). "Chemokines are essential mediators of immune responses, and the CCL20/CCR6 chemokine signaling axis is known to be involved in inflammation, infectious diseases, and cancer progression." (PMID 40853122, 2025). "Data from both databases evaluated that the expression of CCL20 was increased in various cancer tissues, including HCC, than in normal tissues (P < 0.001), and the expression of CCL20 was positively connected with the G grade ((P = 0.002)." (PMID 38493218, 2024). "Functionally, CCL20 knockdown in cancer suppressed M2-like TAM polarization when cultured with CM, whereas CCL20 overexpression suppressed polarization." (PMID 38297161, 2024). "In the present study, pan-cancer analysis identified PDK4, CCL20, and FBL as central genes (hub genes) with significant differences in expression in 17, 14, and 17 cancer types, respectively." (PMID 38914792, 2024). "We selected eight candidates (CST4, CCL20, CX3CL1, CXCL5, CXCL8, GDF15, CCL5 and MMP3) that play an important role in cancer pathogenesis for further study." (PMID 38385965, 2024). "When TGF-β was present, Th17 cells played a pro-cancer role by secreting IL-17 and IL-22, while when IL-1βwas present, Th17 inducing CCL2 and CCL20 expression, DCs, and other immune cells were activated and recruited, resulting the inhibition of COAD." (PMID 39252305, 2024). "In the TCGA pan‐cancer datasets, THYM patients with the T3 subtype exhibited the highest expression of CCL20, as well as the highest CCL20‐CCR6 ligand‐receptor pair score." (PMID 39258580, 2024). "CCL20 and its receptor CCR6 are involved in the progression, migration, invasion and angiogenesis of cancer cells, including HCC cells." (PMID 38493218, 2024). "In malignant tumors, the polarized M2 macrophages produce and secrete cytokines such as CCL18, CCL20, CCL22, IL10, TGFB1, and GDF15." (PMID 39272860, 2024). "Recently, the C-C motif chemokine ligand 20 (CCL20) and its specific chemokine receptor 6 (CCR6) have received tremendous attention in cancer research." (PMID 38730689, 2024). "Other IFNγ-induced chemokines CCL5, CCL20, and CXCL1 were shown to be related to cancer progression and poor prognosis." (PMID 37445941, 2023).